PRKAG2 (protein kinase AMP-activated non-catalytic subunit gamma 2)
Diseases named in the same sentence as PRKAG2 in open-access papers (continued):
Sharing a sentence is not in itself a finding about the gene and the disease.
PRKAG2 also shares sentences with these, for which no sentence is quoted: Noonan syndrome (4 papers); Supraventricular tachyarrhythmias (4); Ventricular hypertrophy (4); amyloidosis (3); familial hypertrophic cardiomyopathy (3); RASopathies (3); cardiac diseases (2); cardiofaciocutaneous syndrome (2); dilated cardiomyopathy (2); hypertrophy (2); left ventricular hypertrophy (2); malformation syndromes (2); mitochondrial disease (2); prostate carcinoma (2); rectal cancer (2); Abdominal obesity (1); alcoholic liver diseases (1); atrial flutter (1); atrioventricular block (1); Bradycardia (1); cardiac arrhythmia (1); cardiac conduction disease (1); Carvajal syndrome (1); conduction disorder (1); congenital heart disease (1); congestive heart failure (1); coronary atherosclerosis (1); COVID-19 (1); deficiencies (1); diabetic kidney disease (1).
A further 41 diseases each share a sentence with PRKAG2 in 1 paper.